IGFBP3 (insulin like growth factor binding protein 3)
Diseases named in the same sentence as IGFBP3 in open-access papers (continued):
Sharing a sentence is not in itself a finding about the gene and the disease.
breast carcinoma (continued). "Moreover, IGFBP3 can promote IGF action in diverse human cells including skin fibroblasts, breast carcinoma cells and prostate cancer cells overexpressing a constitutively active AR." (PMID 29108245, 2017). "Furthermore, an exposure of breast carcinoma cells (MDA-MB231) to IGF-I led an enhanced capacity of cell proliferation, cleavage of IGFBP-3 and activation of IGF-I cell signaling." (PMID 27661126, 2016). "IGFBP-3 regulates the bioavailability of IGF-I and is involved in breast cancer prognosis." (PMID 26251693, 2015). "Early studies investigating the expression of IGFBP-3 in breast cancer cell lines revealed a negative correlation between expression of estrogen receptor (ER) and IGFBP-3." (PMID 26221601, 2015). "This is in contrast other studies in breast cancer survivors who reported correlations between physical activity and several metabolic variables including fasting insulin, HOMA-IR, CRP, leptin, IGF-I and IGFBP-3." (PMID 23855321, 2013). "We next compared 1, 25-D3 and IGFBP-3 treatment on MAPK and Akt activation in parental and resistant cells since it is well documented that IGF-I/MAPK and IGF-I/Akt signalling plays a crucial role in proliferation and survival of breast cancer cells." (PMID 23690781, 2013). "We investigated the association between 89 single nucleotide polymorphisms (SNPs) in 7 cytokine/growth-factor genes (FGFR2, IGFBP1, IGFBP3, TGFB1, TNF, VEGF, IL6) and percent MD in 301 premenopausal women (aged 50 to 55 years) participating in the Norwegian Breast Cancer Screening Program." (PMID 23762340, 2013). "We therefore used the IGFBP3 enhancer as bait in circular chromosome conformation capture with high-throughput sequencing (4C-seq) in normal human mammary epithelial cells (HMEC) and two breast cancer cell lines, MCF7 and MDA-MB-231." (PMID 24019942, 2013). "Adaptations to the model include the addition of breast cancer therapies and their potential influence on biomarkers as well as the addition of insulin-like growth factor 1 (IGF-1) and IGF binding protein 3 (IGFBP-3)." (PMID 23153358, 2012). "Thus, trastuzumab-refractory breast cancer tissue or patient serum should be examined for possible predictors of response to IGF-IR therapy, such as increased IGF-I levels, reduced IGFBP3 levels, or increased expression or phosphorylation of IGF-IR." (PMID 22830017, 2012). "The incidence of breast cancer has been associated with levels of IGF1 and IGFBP3 in premenopausal women in most, but not all studies." (PMID 20302654, 2010). "Among ovarian carcinomas, only a handful such genes have been shown to exhibit DNA promoter hypermethylation, including the Insulin-like growth factor binding protein-3 (IGFBP-3), the Deleted in Lung and Esophageal Cancer 1 (DLEC1), and the breast cancer gene BRCA1." (PMID 17623056, 2007). "In vitro, IGFBP-3 promotes EGF in HER-2-overexpressing T47D and Hs578T breast cancer cells." (PMID 15642160, 2005). "Our findings also showed that the C allele of IGFBP-3 A-202C (SNP rs2854744) correlated with higher circulating IGF-1 levels (rs = 0.175, p ≤ 0.001), which were associated with an elevated likelihood of breast cancer (OR= 1.010; 95%CI, 1.006–1.015) (data not shown)." (PMID 40493660, 2025). "Upon treatment with Ful, IGFBP-3 was induced in breast cancer cells similar to data observed in reports describing the regulation of IGFBP-1 by the G-protein-coupled estrogen receptor (GPER1) and clinical studies showing IGFBP-3 serum increases in response to Ful." (PMID 39619437, 2024). "Postmenopausal breast cancer patients (stages 0–III) who had completed anticancer treatment and received an oral supplement of melatonin (3 mg/day for 4 months) did not significantly improve the levels of serum biomarkers (estradiol, IGF1, IGFBP-3) related to breast cancer." (PMID 35409137, 2022).
breast carcinoma (continued). "In conclusion, this nested case-control study provides evidence that preoperative, but not postoperative IGF-I and IGFBP-3 levels provide independent prognostic information and influence breast cancer recurrence, justifying confirmatory studies with larger numbers of subjects." (PMID 33767994, 2021). "In conclusion, this study suggests that preoperative IGF-I and IGFBP-3 levels, but not postoperative changes, might provide independent prognostic information and influence breast cancer recurrence." (PMID 33767994, 2021). "To evaluate the functional significance of the interaction between GRP78 and IGFBP-3 we manipulated the expression of GRP78 using siRNA and assessed changes in cell survival and invasion of Hs578T and MDA-MB-231 breast cancer cells treated with IGFBP-3 in the presence or absence of GRP78." (PMID 33352865, 2020). "Furthermore, IGFBP-3 has been shown to induce apoptosis by activating caspase-8 cleavage, but not cytochrome c release or caspase-9 cleavage involved in the death receptor-mediated apoptotic pathways in MCF-7 breast cancer cells." (PMID 32443727, 2020). "There has been no consensus over whether IGFBP-3 positively or negatively impacts breast cancer prognosis." (PMID 33352865, 2020). "Exogenous IGFBP-3 treatment to Hs578T breast cancer cells lacking IGF-1R was demonstrated to have little effect on the inhibition of growth, however, treatment with an analog of ceramide could dramatically enhance apoptosis in an IGF-independent manner." (PMID 32478064, 2020). "In addition, we also found that IGFBP-3 had no apparent influence on RFS or OS in HER2-positive breast cancer patients, either overweight or not." (PMID 32391265, 2020). "In an IHC study of breast cancer tissue sections, in which high IGFBP-3 staining showed a trend (non-significant) of association with worse patient survival, “no clear evidence” of nuclear IGFBP-3 staining was reported." (PMID 29623068, 2018). "Similarly, the proportion of cleaved IGFBP3 (which promotes proliferation in breast cancer 43) is greater in nonseminoma patients and declines upon response to treatment." (PMID 29160922, 2018). "In addition, when adjusted by exercise mode in the subgroup analysis, we found that Tai Chi was an effective intervention in increasing IGFBP-3 serum levels in breast cancer survivors, although statistical significance was not reached." (PMID 27562357, 2016). "In addition, levels of IGFBP-3 in breast cancer tissue, determined by IHC but not mRNA levels, were associated with poor OS." (PMID 26217584, 2015). "Overall, it appears that understanding the diverse abilities of IGFBP3 is certainly not straightforward, and more mechanistic studies, possibly on breast cancer stem cells, are needed to establish whether IGFBP3 could be exploited in breast cancer therapy." (PMID 25374561, 2014). "Given the reduced expression of IGFBP3 in the C3.6 cells, IGFBP3's reported role in regulating IGF activity and the reported aberrant regulation of the IGF system in breast cancer, we wanted to further examine if IGF1-induced signalling might be affected by ErbB2 overexpression in these cells." (PMID 20840765, 2010). "In summary, results from this large collaborative study support previous evidence that specific genetic variants in IGF1 and IGFBP3 genes significantly influence circulating levels of IGF-I and IGFBP-3, respectively, but have no measurable effect on breast cancer risk." (PMID 18596909, 2008). "High levels of recombinant nonglycosylated IGFBP-3 can induce apoptosis in MCF-7 breast carcinoma cells, although under some conditions these levels of exogenous IGFBP-3 may induce apoptosis indirectly by sequestering anti-apoptotic IGFs from the IGFRI." (PMID 16600019, 2006). "The possible difference in associations of IGF-I and IGFBP-3 and risk by menopausal status suggests that high levels of IGF-I and/or low levels of IGFBP-3 may be important in breast cancer development in younger, but not older, women." (PMID 15756268, 2005).
breast carcinoma (continued). "This study suggests that IGFBP-3 expression in breast cancers might be associated with a shorter OS and DFS, although few patients were negative for IGFBP-3 expression." (PMID 15642160, 2005). "IGFBP-3 is not an independent prognosticator for overall survival or disease-free survival, to reflect its dual effects on breast cancer growth regulated by complex pathways in vivo that may relate to its interactions with other growth factors." (PMID 15642160, 2005). "On the contrary, IGFBP-3 has been shown to enhance the survival of cells subjected to glucose starvation and hypoxia by inducing autophagy in a GRP78-dependent manner in human breast cancer cells, which suggests that IGFBP-3 may play a key role in mediating an autophagic survival response." (PMID 32443727, 2020). "However, our study reinforces the conclusion that, since both fingolimod and gefitinib are FDA-approved drugs (though not for breast cancer), inhibiting IGFBP-3-dependent oncogenic signaling by F + G therapy is a plausible approach to targeting basal-like TNBC tumors." (PMID 29623068, 2018). "Further, antiestrogens Ful and Tam induced IGFBP-3 expression in breast cancer cells regardless of subtype, and GPER1 promoted the expression of IGFBP-3 via activation of YAP/TAZ in TNBC cells." (PMID 39619437, 2024). "We examined the basal abundance of GRP78 and IGFBP-3 in nonmalignant MCF-10A cells and breast cancer cell lines using Western blotting." (PMID 33352865, 2020). "Across all cases, overall survival and breast cancer-specific survival, unadjusted for confounders, did not vary by expression of IGF1, IGF1R, IGFBP2, or IGFBP3." (PMID 25619494, 2015). "Breast cancer specimens show a positive correlation between ER status and IGF receptor status, and also a negative correlation between ER status and IGFBP3 expression." (PMID 9413957, 1997). "Furthermore, associations between pre- and postoperative levels of circulating IGF-I, IGFBP-3, and IGFBP-7 and breast cancer recurrence have not yet been studied." (PMID 33767994, 2021). "However, recent studies also showed that IGFBP-3 mutants that failed to translocate to the nucleus and lost binding ability to RXR-α, still induced apoptosis in breast cancer cells." (PMID 32443727, 2020). "Therefore, despite a report that ΔNp63α can downregulate IGFBP-3 in squamous epithelial cell lines, this does not appear to be a likely mechanism of IGFBP-3 downregulation by DNA-damaging drugs in breast cancer cell lines." (PMID 26378048, 2015). "However, no induction of apoptosis was observed in Hs578T breast carcinoma cells exposed to exogenous IGFBP-3 alone, although in this study IGFBP-3 augmented the cellular response to apoptotic stimuli." (PMID 16600019, 2006). "This cell surface IGFBP-3R interacts specifically with IGFBP-3 but not with other high-affinity IGFBPs, activates procaspase-8, and mediates IGFBP-3-induced apoptosis in many different types of cancer cells and tumor suppression in both prostate and breast cancer xenograft mouse models." (PMID 32443727, 2020). "MCF-7 breast cancer cells treated with exogenous IGFBP-3 showed increased apoptosis and this effect could be reversed by the use of non-IGFBP-binding IGF-1analog but not IGF-1 strongly indicating that IGFBP-3 induced apoptosis by sequestering IGF-1 from the receptor." (PMID 32478064, 2020).
prostate carcinoma (120 papers, 2001 to 2025). A carcinoma that arises from epithelial cells of the prostate gland. "In prostate cancer, IGFBP3 causes resistance to poly(adenosine diphosphate-ribose) polymerase (PARP) inhibitors through interaction with DNA-PKcs and EGFR." (PMID 41199784, 2025). "The plasma levels of insulin-like growth factor-I (IGF-I) and its main circulating binding protein, IGF binding protein-3 (IGFBP-3), have been associated with the risk of prostate cancer." (PMID 38542079, 2024). "Approximately 2% of the male population have high levels of IGF-I as well as low levels of IGFBP-3, which is associated with a high risk of suffering advanced prostate cancer with metastasis." (PMID 38542079, 2024). "In observational analyses, men with higher circulating IGF-II and IGFBP-3 had an elevated risk of overall prostate cancer (OR per 1-SD increment = 1.06: 95% CI 1.02, 1.11; P = 0.01; and 1.08: 1.04, 1.11; P <0.0001, respectively)." (PMID 35726641, 2023). "For IGF-I and IGFBP-3, mutual adjustment slightly attenuated the associations with overall prostate cancer risk, but both these associations remained." (PMID 35726641, 2023). "Following further adjustment for IGF-I, the associations with overall disease were attenuated although IGFBP-3 remained significantly associated with overall prostate cancer." (PMID 35726641, 2023). "In our observational analyses, IGF-II, IGFBP-1 and IGFBP-3 were positively associated with overall prostate cancer, but we were underpowered to detect associations with aggressive or early-onset disease." (PMID 35726641, 2023). "We aimed to investigate the associations of IGF-I, IGF-II, IGFBP-1, IGFBP-2 and IGFBP-3 concentrations with overall, aggressive and early-onset prostate cancer." (PMID 35726641, 2023). "Men with higher IGF-II (1.06: 1.02, 1.11) and IGFBP-3 (1.08: 1.04, 1.11) had higher risks of overall prostate cancer, whereas higher IGFBP-1 was associated with a lower risk (0.95: 0.91, 0.99); these associations were attenuated following adjustment for IGF-I." (PMID 35726641, 2023). "Recent research found that overexpression of IGFBP3 was associated with tumour recurrence and poor patient survival through analysis of human prostate cancer specimens and TCGA patient cohorts." (PMID 36168930, 2022). "Our Mendelian randomization results showed a positive association between IGFBP-3 levels and prostate cancer, as previously reported from observational and Mendelian randomization studies." (PMID 35237523, 2022). "Loss in IGFBP3 expression increased the response of the U251 human glioblastoma cell line to CA 125, and enhanced antitumor action of DZ-50 in prostate cancer." (PMID 34737677, 2021). "Nuclear expression of IGFBP3 was reported to be associated with decreased prognosis-free survival time of patients with prostate cancer." (PMID 32414222, 2020). "Conversely, higher serum IGFBP-3 is associated with a lower risk of developing advanced-stage prostate cancer and studies show an increase in IGFBP-3 beginning within months of androgen withdrawal." (PMID 32056047, 2020). "Circulating levels of IGF1 and IGFBP3 has been linked to all cause mortality in men with advances prostate cancer and risk of developing prostate cancer." (PMID 28966806, 2017). "DZ-50 treatment of human prostate cancer cells and cancer-associated fibroblasts (CAFs) downregulated IGFBP3 expression at mRNA and protein level." (PMID 29108245, 2017). "Our findings taken together with clinical evidence that IGFBP3 promoter polymorphism contributes to prostate cancer risk, and its potential biomarker value in prostate cancer patients, support the clinical significance of IGFBP3." (PMID 29108245, 2017). "We observed associations of post-diagnosis serum IGF-I and IGFBP-3 levels with changes in protein intake and changes in adherence to recommendations on fruits and vegetables, BMI, and physical activity following a prostate cancer diagnosis." (PMID 28646365, 2017).
prostate carcinoma (continued). "The IGFBP-3 -202A/C single nucleotide polymorphism was positively associated with prostate cancer (pooled OR for A/C vs. AA = 1.22; 95% CI 0.84, 1.79; OR for C/C vs. AA = 1.51; 1.03, 2.21, n = 8 studies)." (PMID 28361446, 2017). "The focus on nuclear localization of IGFBP3 takes particular significance as the nuclear protein (IGFBP3) has been previously associated with human prostate cancer recurrence." (PMID 29108245, 2017). "Expression of nuclear IGFBP-3 in prostatic cancer tissue was also associated with decreased PFS time." (PMID 26217584, 2015). "In prostate cancer, high serum level of IGFBP-3 correlated with increased cancer risk and cancer specific death." (PMID 26217584, 2015). "Epidemiological studies show that high levels of IGF1 and low levels of IGFBP3 are associated with an increased risk for several common cancers, including cancer of the prostate, breast, lung, and colorectum." (PMID 23527244, 2013). "It has been reported that IGFBP3 is frequently methylated and significantly associated with a poor prognosis in early-stage non-small-cell lung, ovarian, and prostate cancer." (PMID 22401581, 2012). "The present study corroborates previous findings on the IGFBP3-202 A>C CC genotype risk for prostate cancer and high-grade disease." (PMID 22792137, 2012). "Other studies have shown that elevated IGFBP-3 expression is associated with reduced risk of gastric cancer and prostate cancer." (PMID 18498652, 2008). "Most (90%) circulating IGF-I is bound to IGF binding protein-3 (IGFBP-3) and associations of IGFs with prostate cancer are generally strongest with the molar ratio (IGF-I/IGFBP-3) or in statistical models controlling for IGFBP-3." (PMID 12771980, 2003). "Further, following incubation of LNCaP cells with melatonin, genomic microarray found the indolamine to upregulate insulin-like growth factor-binding protein 3 (IGFBP3), a gene target determined to underlie the melatonin-mediated NE differentiation of prostate cancer cells." (PMID 37191417, 2023). "Higher serum IGFBP-3 is associated with a lower risk of developing advanced-stage prostate cancer." (PMID 32056047, 2020). "Intriguingly, while nuclear interactions of IGFBP-3 have been associated with its induction of apoptotic death in prostate cancer cell lines, a clinical study showed that high nuclear staining of IGFBP-3 in prostate cancer tissue was prognostic for earlier disease recurrence." (PMID 29623068, 2018). "Higher serum levels of IGF-1 and lower levels of IGFBP-3 have been associated with increased risk of aggressive prostate cancer although higher levels of IGFBP-3 have been observed in prostate tumor cells compared to benign cells, and are associated with higher cancer recurrence." (PMID 28417914, 2017). "Additionally, the treatment arm modified the association of 25(OH)D with prostate cancer among individuals with higher serum IGFBP-3 (OR, finasteride: 0.83, 95% CI: 0.61–1.12; OR, placebo: 1.26, 95% CI: 0.98–1.63; p for interaction = 0.03)." (PMID 28417914, 2017). "Low IGFBP-3 levels are associated with greater risk of aggressive prostate cancers." (PMID 28005952, 2016). "We hypothesized that the functional polymorphisms in IGF-I and IGFBP-3 may be associated with the risk of prostate cancer (PCa) in the Chinese population." (PMID 24586243, 2014). "SNPs in the IGF-I and IGFBP-3 associated with the prostate cancer risk." (PMID 24586243, 2014). "Furthermore, it was also found that the IGFBP3-202 A>C SNP was associated with prostate cancer and with low circulating levels of IGFBP3." (PMID 22792137, 2012).